CRP (C-reactive protein)
Diseases named in the same sentence as CRP in open-access papers (continued):
Sharing a sentence is not in itself a finding about the gene and the disease.
lower respiratory tract infections (continued). "One approach to improving antibiotic stewardship in primary care may be to support all General Practitioners (GPs) to have access to point of care C-Reactive Protein tests to guide their prescribing decisions in patients presenting with symptoms of lower respiratory tract infection." (PMID 31527896, 2019). "Second a mixed group of medical and surgical patients were included; whether CRP will have a better performance in a particular subgroup of patients, for example in patients with lower respiratory tract infection remains uncertain, but deserves further investigation." (PMID 20875120, 2010). "He required admission with dyspnoea in 2011 and had a C-reactive protein (CRP) level of 262 mg/L (<5) at that time, presumed related to lower respiratory tract infection." (PMID 41293159, 2025). "This association was highlighted in a recent systematic review encompassing 13 studies and a total of 9844 subjects, which evaluated the impact of CRP-POC testing on antibiotic prescribing in adults and children with upper and lower respiratory tract infections." (PMID 41471239, 2025). "We have the microbiological tests, and we still use CRP for certain situations in which the aetiology isn’t clear, for example, when tests are negative, and you have a lower respiratory tract infection." (PMID 40921638, 2025). "PCT is a more applicable and accurate biomarker for identifying the bacterial (high PCT) as opposed to viral (low PCT) origin of lower respiratory tract infections than CRP." (PMID 37627950, 2023). "Nonetheless, some of the GPs criticized the misuse of the CRP test, which was often used solely to convince patients that antibiotics were unnecessary rather than to test for lower respiratory tract infections in adults (G1, G7, G8)." (PMID 35501699, 2022). "The control group provided usual care without CRP POCT for patients with suspected lower respiratory tract infections." (PMID 34548288, 2021). "The IPF% values in patients with lower respiratory tract infections had no linear correlation with CRP values in these patients (r = 0.076, p = 0.62)." (PMID 32821576, 2020). "There is no linear correlation between IPF values and CRP values in patients with lower respiratory tract infections." (PMID 32821576, 2020). "The potential use of CRP in differentiating bacterial from non-bacterial lower respiratory tract infection has been repeatedly suggested." (PMID 27439403, 2016). "Thirty-eight patients (63%) in each group were diagnosed with Upper Respiratory Tract Infections with 19 (32%) and 16 (27%) diagnosed with Lower Respiratory tract infections in the 'No CRP' and 'CRP' groups respectively." (PMID 21880122, 2011). "Research by Ciccone and colleagues suggests that using a C-reactive protein guided approach to the evaluation of young children with lower respiratory tract infections may help reduce antimicrobial prescription without increasing rates of treatment failure." (PMID 39288196, 2024). "However, in our study, the IPF% values in patients with lower respiratory tract infections had no linear correlation with CRP values in these patients (r = 0.076, p = 0.62)." (PMID 32821576, 2020). "They claimed that serum CRP could be used instead of procalcitonin to diagnose lower respiratory tract infections and determine whether they needed antibiotics or not." (PMID 30234089, 2018). "Point-of-care C-reactive protein (CRP) testing is widely accepted in Dutch general practice for adult patients with acute cough, but GPs’ perceptions of its use in children with suspected lower respiratory tract infection (LRTI) are unknown." (PMID 30564689, 2018). "A previous large study, looking at the effect of CRP testing and or communication skills on antibiotic use in lower respiratory tract infections, found a slight increase in re-consultation rates using CRP measurement, however this increase was not statistically significant." (PMID 21880122, 2011).
lower respiratory tract infections (continued). "Although CRP is not a specific inflammatory factor for COPD, it aids in clinical decision-making concerning the administration of antimicrobial agents for lower respiratory tract infections in COPD patients." (PMID 37400821, 2023). "Due to frailty, low immunity, and poor nutritional status, the hemogram, CRP, PCT, and other inflammatory indexes in the elderly are often not positively correlated with lower respiratory tract infection." (PMID 33849586, 2021). "CRP: C-reactive protein; GP: general practitioner; LRTI: lower respiratory tract infection; NA: not applicable; POCT: point-of-care test." (PMID 33153517, 2020). "CRP, an inflammatory marker, was found to be significant by the GNB model, consistent with evidence supporting its utility in differentiating bacterial from non-bacterial lower respiratory tract infections." (PMID 40941745, 2025). "The aim of the study was to assess the ability of PCT or CRP combined with clinical characteristics to distinguish between viral and bacterial infections in hospitalized non-intensive care unit (ICU) adults with lower respiratory tract infection (LRTI)." (PMID 34583675, 2021). "Randomized controlled studies using CRP and PCT to guide antibiotic decisions have been shown to reduce antibiotic prescriptions without increased morbidity for both URI and lower respiratory tract infection (LRI)." (PMID 28991170, 2017).
meningitis (80 papers, 2006 to 2026). A disorder characterized by acute inflammation of the meninges of the brain and/or spinal cord. "Consistent with prior studies, our findings demonstrate that WBC counts and CRP levels at the onset of meningitis lack sufficient diagnostic utility, as the recorded values were all within normal ranges." (PMID 41322089, 2025). "Elevated CRP (CRP ≥8 mg/L) was associated with greater risk of developing meningitis or death in a time-to-event analysis (hazard ratio = 2.70; 95% CI, 1.12–6.25; P = .026)." (PMID 39086467, 2024). "Rather, our data suggest that increasing CRP is associated with an increased risk of meningitis or death in persons with CrAg titer <1:160, whereas an inverse trend is seen in persons with CrAg titer ≥1:160." (PMID 39086467, 2024). "When investigating baseline CRP as a potential predictor for meningitis or death in persons with HIV-associated cryptococcal antigenemia, we evaluated an interesting and potentially important interaction between CRP and CrAg titer." (PMID 39086467, 2024). "In conclusion, we identified that elevated serum CRP initially appears to be associated with the development of meningitis or death in persons with HIV and asymptomatic cryptococcal antigenemia." (PMID 39086467, 2024). "We hypothesized that CRP might also be associated with meningitis or death in persons with cryptococcal antigenemia." (PMID 39086467, 2024). "The purpose of this study is to characterize the baseline CRP distribution among people with asymptomatic cryptococcal antigenemia and to evaluate whether elevated baseline CRP is a risk factor for meningitis or death." (PMID 39086467, 2024). "Remarkably, we expounded for the first time that the microbiota composite pattern was associated with CRP in blood and the granulocyte proportion, supporting a valuable role of the candidate microbiome in reflecting meningitis infection and the inflammatory state." (PMID 34100633, 2021). "According to the univariate analysis, the risk factors of meningitis were patients < 12 months of age (OR: 16.04, P = 0.009), septic shock (OR: 23.4, P = 0.013), vomit (OR: 13.33, P < 0.001), convulsion (OR: 15.86, P < 0.001), CRP ≥ 40 g/L (OR: 5.56, P = 0.009), and higher PCT (OR: 1.05, P = 0.013)." (PMID 36040531, 2022). "Meningitis/disseminated patients had lower lymphocyte counts, higher CRP, more frequent LP (82.5% vs. 14.7%), higher CSF smear positivity (57.6%), and more frequent meningitis-related MRI changes." (PMID 41485003, 2026). "Meningitis (adjusted OR 11.53, p = 0.01), the need for fluid bolus (adjusted OR 16.8, p = 0.01), and peak CRP levels (adjusted OR 1.01, p = 0.03) emerged as significant predictors of combined mortality and neurodisability." (PMID 39825283, 2025). "WBC count, neutrophil count, and CRP levels in the encephalitis group were significantly elevated compared to both the meningitis and myelitis groups (p < 0.05)." (PMID 40066307, 2025). "On day 15, he was diagnosed with GBS septicemia and meningitis, as evidenced by abnormal cerebrospinal fluid (CSF) profiles and a peak C-reactive protein (CRP) level of 183 mg/L." (PMID 40432991, 2025). "Of the 94 persons with elevated CRP, 19 (20.2%) developed meningitis or death, whereas of the 88 persons with normal CRP, 8 (9.1%) developed meningitis or death (P = .035)." (PMID 39086467, 2024). "In England, the National Institute for Health and Care Excellence (NICE) guidelines for meningitis, fever in children < 5 years, and neonatal infections recommended the use of CRP in similar terms to the Dutch guidelines." (PMID 38504318, 2024). "These patterns of observation are valuable, but we posit that the limitations of this study make it difficult to declare CRP a predictor for meningitis or death in cryptococcal antigenemia." (PMID 39086467, 2024). "Using time-to-event analyses, we compared 24-week meningitis-free survival in persons with normal CRP (<8 mg/L) and elevated CRP (≥8 mg/L)." (PMID 39086467, 2024).
meningitis (continued). "The most important variables in descending order were the history of previous meningitis and CRP level." (PMID 39338252, 2024). "A random forest model identified previous meningitis history and serum CRP level as key predictors of HSV-2 meningitis." (PMID 39338252, 2024). "Compared to meningitis, patients with encephalitis more often had elevated C-reactive protein, LP was performed later and showed lower pleocytosis, and brain imaging was significantly more pathological, showing evidence of cerebral vasculitis in half of them." (PMID 38957692, 2024). "Clinical factors, including history of previous meningitis and CRP level, were important factors in the predictive model, which suggested that basic clinical practices are valuable for diagnosis even in the absence of a PCR test." (PMID 39338252, 2024). "We found PTX3 to be non-detectable or very low in the CSF in a control group despite clinical suspicion of meningitis and other inflammatory activity as indicated by elevated CRP and leukocytes in the blood." (PMID 36862691, 2023). "On laboratory examinations, C reactive protein increased, CSF examination showed features of meningitis, and hemorrhagic meningoencephalitis was observed on cerebral MRI." (PMID 37443518, 2023). "In contrast, the mean CRP and WBC counts at the time of admission were statistically higher in patients with associated meningitis (CRP: 19.81 ± 12.56 mg/dl vs. 11.63 ± 11.08 mg/dl, p = 0.001; WBC: 14.7 ± 7.76 g/l vs. 10.88 ± 5.11 g/l, p = 0.005)." (PMID 38020984, 2023). "Factors used in diagnosing meningitis included body temperature, protein levels, CSF-to-blood glucose ratio, CSF white cell counts, lactate, glucose, erythrocyte sedimentation rate, and C-reactive protein (CRP)." (PMID 37942080, 2023). "The relationship between white blood cells (WBC), erythrocyte sedimentation rate (ESR), and C-reactive protein in meningitis was evaluated." (PMID 37349740, 2023). "Blood check indicators for infections such as C-reactive protein, full blood count, and blood cultures are conducted if anyone is suspected of having meningitis." (PMID 33401658, 2021). "C-Reactive Protein (CRP) of neonates with meningitis was twice higher than normal cases, and leukocytes and proteins in the CSF in neonates with meningitis were higher than healthy ones." (PMID 32494342, 2020). "Increased leukocytes and protein of CSF and also CRP and Urea were laboratory findings of meningitis." (PMID 32494342, 2020). "The result of a study showed that CRP level of cerebrospinal fluid in neonates with purulent meningitis was higher than aseptic meningitis." (PMID 32494342, 2020). "Infants who developed meningitis were more likely to manifest altered level of consciousness (66.7% vs. 33.9%, P = 0.018), seizure (50% vs. 24.6%, P < 0.001), and CRP elevation (91.7% vs. 45.6%, P = 0.004)." (PMID 31537886, 2019). "The patients with meningitis had increased peripheral leucocyte counts, increased levels of C-reactive protein (CRP) and CSF protein, cells and erythrocytes and a higher CSF/serum albumin ratio." (PMID 29881343, 2018). "The mean maximum CRP was 56.7mg/L, with 22 cases (11.1%) having a maximum CRP level of <10mg/L in their meningitis infection; this represents a sensitivity of 88.9% for that cut-off in all neonatal meningitis." (PMID 30509228, 2018). "On admission, four patients had elevated liver enzyme or bilirubin levels, C-reactive protein was high in four patients, two were thrombocytopenic, one had hepatic cytolysis, and one had meningitis/meningoencephalitis." (PMID 29090679, 2017). "All studies comparing CRP levels in blood specimen of patients with meningitis (5/5) reported statistically significant differences in CRP levels between the bacterial and viral group, with higher levels seen in bacterial infections." (PMID 27486746, 2016).
meningitis (continued). "An additional two was classified as organ/space SSI, where one presented with headache and brain abscess, and the other with fever, elevated CRP and meningitis due to penetration through the skin of the scalp." (PMID 25122445, 2014). "In epidemiologic study, measured IL6 of CSF is important and useful in diagnosis of meningitis.In 12 patients with viral meningitis, serum CRP level was normal." (PMID 23483792, 2012). "All patients in the subgroup with febrile non-CNS infection had elevated CRP levels with a median of 28 mg/L (range 6–174 mg/L) compared to the subgroup with complex febrile seizures (median CRP 10 mg/l; range 0–108 mg/L) and the subgroup with meningitis (1.5 mg/L; 0–20 mg/L)." (PMID 38539395, 2024). "We found that CRP ≥8 mg/L appeared to mitigate the protective effect of low CrAg titer in our population, with meningitis or death events rising from ∼5% in persons with CRP <8 mg/L and titer CrAg <1:160 to ∼20% in persons with CRP ≥8 mg/L and CrAg titer <1:160." (PMID 39086467, 2024). "Our findings demonstrate that CrAg titer may modify the direction of effect of CRP with meningitis-free survival; future studies should account for this interaction." (PMID 39086467, 2024). "C-reactive protein (CRP), tumor necrosisfactor-α (TNF-α), interleukin-1β (IL-1β), interleukin-6(IL-6), procalcitonin (PCT) are considered beingclosely implicated in the presence and progression ofpurulent meningitis." (PMID 39139150, 2024). "The prediction model suggested that the clinical history of previous meningitis and serum CRP level may guide clinical assessment of meningitis." (PMID 39338252, 2024). "Mean C-reactive protein (CRP) and white blood cell (WBC) counts at time of admission were statistically higher in patients with associated meningitis (CRP: 19.81 ± 12.56 mg/dl vs. 11.63 ± 11.08 mg/dl, p = 0.001; WBC: 14.67 ± 7.76 g/l vs. 10.88 ± 05.11 g/l, p = 0.005." (PMID 38020984, 2023). "The mean CRP and WBC counts were elevated in all patients at the time of admission, whereas they were respectively higher in patients with an associated meningitis (CRP: 19.81 ± 12.57 mg/dl vs. 11.63 ± 11.8 mg/dl, p = 0.001; WBC: 14.67 ± 7.76 g/l vs. 10.88 ± 5.11 g/l, p = 0.005)." (PMID 38020984, 2023). "In addition to young age, the presentations of septic shock, vomit, convulsion, CRP ≥ 40 g/L, and higher level of PCT on admission were statistically related to an increased risk of developing meningitis." (PMID 36040531, 2022). "This may be due to its low levels in bacterial meningitis in our study which could be attributed to measuring serum CRP within the first hours of suspected meningitis." (PMID 34115780, 2021). "In another study, 72% of neonates with meningitis showed CRP level higher than 8 mg/Dl." (PMID 32494342, 2020). "The NICE GDG may well have been attempting to ensure all neonates with meningitis were included by selecting a specific CRP for their LP criteria." (PMID 30509228, 2018). "Because of the low incidence of neonatal meningitis, few studies have been done on the CRP rises in neonatal meningitis, and those done have small numbers: the sensitivity of a CRP > 10mg/L cut-off has been suggested to be 76.3% in one study, and a CRP > 40mg/L to be 72.7% at 24h." (PMID 30509228, 2018). "Poor hospital outcome was associated with weight <2.5 kg, dyspnea, pallor, signs of meningitis, an elevated C-reactive protein and an ANC <1500/mm3; but not with skin infection or hot bed exposure." (PMID 23902672, 2014). "Gary in 1986 measured CRP in CSF of 145 patients with meningitis." (PMID 23483792, 2012). "There was no worsening of inflammatory markers, ie, serum CRP and peripheral white blood cell counts, at the onset of meningitis (mean ± SD CRP: 4.3 ± 4.1 mg/dL, WBC: 9,300 ± 7,700/μL), as compared with the levels at admission (mean ± SD CRP: 5.9 ± 2.0 mg/dL, WBC: 14,800 ± 9,000/μL)." (PMID 21917158, 2011).